IGFBP5 (insulin like growth factor binding protein 5)
Diseases named in the same sentence as IGFBP5 in open-access papers (continued):
Sharing a sentence is not in itself a finding about the gene and the disease.
Glucose intolerance (4 papers, 2015 to 2023). Glucose intolerance (GI) can be defined as dysglycemia that comprises both prediabetes and diabetes. "IGFBP-5 chromosomal deletion and low expression are associated with increased adiposity and marked glucose intolerance." (PMID 37891752, 2023). "IGFBP-5 concentrations are reduced in individuals with type 1 and type 2 diabetes, IGFBP-5 deficient mice have an increase in size, mild glucose intolerance, and increased adiposity when compared to wild type mice." (PMID 30392760, 2019). "IGFBP5 gene expression was successfully downregulated in TMSCs following 80 nM siRNA treatment, and IGFBP5 knockdown partially reversed the protective effects of TMSCs on HFD-induced glucose intolerance." (PMID 31018536, 2019). "Finally, proteomic analysis revealed high secretion of insulin-like growth factor-binding protein 5 by TMSCs, and its expression was critical for the protective effects of TMSCs against HFD-induced glucose intolerance and ER-stress response in pancreatic islets." (PMID 31018536, 2019).
intervertebral disc degeneration (4 papers, 2019 to 2023). "However, IGFBP5 overexpression can promote the proliferation and inhibit the apoptosis of rat nucleus pulposus cells derived from intervertebral disc degeneration by inducing inactivation of the ERK/MAPK axis." (PMID 37078747, 2023). "On the contrary, miR-24-3p upregulation could promote intervertebral disc degeneration through IGFBP5 and the ERK signaling pathway." (PMID 34116684, 2021). "Therefore, strategies to maintain the expression or to prevent the repression of IGFBP5 have the potential to serve as possible therapeutic and/or preventive approaches for degenerative disc disease." (PMID 31290273, 2019). "In degenerative nucleus pulposus cells from patients with intervertebral disc degeneration, miR-24-3p was shown to target the 3’-UTR of IGFBP-5 mRNA, downregulating IGFBP-5 and enhancing ERK activation." (PMID 35597813, 2022).
lymph node metastasis (4 papers, 2009 to 2023). "This trend was associated with clinicopathological stage, lymph node metastasis, and the degree of cell differentiation such that greater tumor differentiation and later clinical stages of CC were linked to lower levels of IGFBP-5 expression." (PMID 19476635, 2009). "Reports suggest that IGFBP-5 is either elevated or decreased in lymph node metastases and a high IGFBP-5/IGFBP-4mRNA expression ratio is related to decreased survival with poor prognosis." (PMID 27050076, 2016).
papillary thyroid carcinoma (4 papers, 2020 to 2024). "For example, miR-204-5p normally suppresses IGFBP5, however miR-204-5p is downregulated in papillary thyroid carcinoma (PTC), thereby enhancing IGFBP5 expression." (PMID 36465383, 2022). "And IGFBP5 can reversed the anti-proliferation effects of miR-204-5p in papillary thyroid carcinoma." (PMID 32127912, 2020). "In papillary thyroid carcinoma, IGFBP-5 was reported to promote cell growth, and miR-204-5p, which inhibits growth by suppressing IGFBP-5, was downregulated in these cells." (PMID 32194505, 2020).
rheumatoid arthritis (4 papers, 2019 to 2026). A chronic, systemic autoimmune disorder characterized by inflammation in the synovial membranes and articular surfaces. "Clinical implication of IGFBP5 changes was investigated using rheumatoid arthritis (RA) and acute lung injury (ALI) models." (PMID 39867883, 2024).
type 2 diabetes (4 papers, 2017 to 2025). "Prior research has indicated that both IGFBP7 and IGFBP5 have significant roles in the progression of type 2 diabetes and its related complications." (PMID 40444232, 2025).
urothelial carcinoma (4 papers, 2015 to 2024). A malignant neoplasm derived from the transitional epithelium of the urinary tract (urinary bladder, ureter, urethra, or renal pelvis). "A recently published study indicated the important role of IGFBP5 in tumor progression in urothelial carcinoma and associated IGFBP5 over-expression with advanced tumor stage, frequent mitosis and poorer clinical outcomes." (PMID 26569312, 2015).
adenomyosis (3 papers, 2022 to 2025). The growth of endometrial tissue inside the muscular wall of the uterine corpus. "Collectively, these findings propose that SFRP4+IGFBP5hi NKT cells may drive stem cell differentiation toward neurogenic lineages through IGFBP5 expression, thereby contributing to adenomyosis-associated pain." (PMID 39936948, 2025). "Overall, single-cell analyses have revealed the complex interplay of cellular and molecular mechanisms driving adenomyosis, highlighting the potential for therapeutic interventions targeting Wnt signaling, angiogenic pathways, and pain-associated stem cell markers such as IGFBP5 and SFRP4." (PMID 39936948, 2025). "Next, topological analysis using the cytoHubba plugin in Cytoscape identified MMP7, MMP11, SERPINA1, THBS1, and IGFBP5 as candidate hub genes expressed in both adenomyosis and endometriosis." (PMID 41272701, 2025). "While MMP7 exhibited the highest expression in the co-existent group (p < 0.0001), MMP11 and IGFBP5 showed maximum expression in women with adenomyosis (p < 0.0001)." (PMID 41272701, 2025). "The expression of IGFBP5 was positively correlated with the pain scores of adenomyosis patients." (PMID 36532077, 2022). "Out of these, significant overexpression of MMP7, MMP9, MMP11, IGFBP5, and TIMP1 was observed at both gene and protein levels in adenomyosis as compared to endometriosis." (PMID 41272701, 2025). "The expression of IGFBP5, an estrogen-regulated molecule and substrate of MMP11, was also the highest in adenomyosis and lowest in the co-existent group." (PMID 41272701, 2025). "This points to IGFBP5 and NEFM as potential therapeutic targets for managing pain in adenomyosis patients." (PMID 39936948, 2025). "On comparing adenomyosis patients with controls, significant differences were observed in the expression of MMP9, MMP11, SERPINA1, IGFBP5, and TIMP1 (p < 0.05); however, MMP7 and THBS1 remained comparable." (PMID 41272701, 2025). "IGFBP5, and PEMPA1 were presented high expression in the adenomyosis pain group (log2(FC)>1)." (PMID 36532077, 2022). "However, in the present experiment, although we confirmed the presence of a large number of undifferentiated cells in the adenomyosis pain group, there was no further evidence on the biological functions of SFRP4 and IGFBP5." (PMID 36532077, 2022).
cervical cancer (3 papers, 2009 to 2024). A primary or metastatic malignant neoplasm involving the cervix. "The expression of these hub genes were verified through TCGA, GEPIA, qRT-PCR, and immunohistochemistry, and it was found that TOP2A, AURKA as well as CCNA2 were overexpressed and IGFBP5 was low expression in cervical cancer." (PMID 39060960, 2024). "It was found that TOP2A, AURKA, CCNA2 and IGFBP5 could be all potential tumor markers for cervical cancer." (PMID 39060960, 2024). "This study showed that TOP2A, AURKA, CCNA2 and IGFBP5 screened through bioinformatics analysis were significantly differentially expressed in cervical cancer samples compared with normal samples, which might be biomarkers of cervical cancer." (PMID 39060960, 2024). "TOP2A, AURKA and CCNA2 were overexpressed in cervical cancer, while IVL and IGFBP5 were low expression in cervical cancer." (PMID 39060960, 2024). "The TOP2A, AURKA and CCNA2 in cervical cancer were significantly increased, while IVL, KRT1, and IGFBP5 were significantly decreased, compared with normal tissues, which was consistent with the screening results." (PMID 39060960, 2024). "Analysis of IGFBP-5 and cFLIP expression levels, may be useful tools for clinical diagnosis and differential diagnosis of CIN and cervical cancer." (PMID 19476635, 2009). "However, interestingly, the TCGA database and GEPIA online website analysis showed that TOP2A, AURKA, CCNA2 and IVL were overexpressed and IGFBP5 was low expression in cervical cancer, and there was no statistical difference in the expression of KRT1 in cervical cancer tissue and normal tissue." (PMID 39060960, 2024).
cognitive deficits (3 papers, 2022 to 2025). "IGFBP5 can modulate lipid metabolism and insulin sensitivity, which are both associated with the cognitive impairment." (PMID 37434738, 2023). "Hence, elevated IGFBP5 expression could be responsible for some of the early cognitive deficits that occur during the course of Alzheimer’s disease." (PMID 35513854, 2022). "While there is no literature to our knowledge regarding a role of IGFBP5 in FXS, insulin signaling underlies circadian and cognitive deficits in FXS flies and mice." (PMID 40649914, 2025).
dementia (3 papers, 2019 to 2024). Loss of intellectual abilities interfering with an individual's social and occupational functions. "The elevated expression of IGFBP-2 and IGFBP-5 in the brain is of both all-cause dementia and Alzheimer’s disease." (PMID 38473707, 2024). "Therefore, future clinical trials should examine the association between IGFBP5 serum or CSF levels, structural brain magnetic resonance imaging, cognitive performance, and the incidence of dementia and AD in a large, prospective cohort of cognitively healthy adults." (PMID 35513854, 2022). "Elevated IGFBP5 protein levels have been detected in the CSF of AD patients, but it remains to be established whether IGFBP5 levels in serum or CSF can predict adverse cognitive outcomes, including dementia risk, over time." (PMID 35513854, 2022). "While almost half of the participants showed clinical dementia proximate to death, the association of IGFBP5 and motor function did not vary between individuals with and without dementia (IGFBP5 x Dementia, Estimate, -0.011, S.E., 0.025, p = 0.651)." (PMID 31404102, 2019). "Given the growing interest in dementia therapeutics targeting impaired insulin metabolism and IGF signaling, IGFBP5 may be a useful circulating biomarker to predict dementia risk for future clinical trials." (PMID 35513854, 2022). "To insure that these findings were not driven by poor cognition in individuals with dementia proximate to death, we added an interaction term between IGFBP5 and global cognition score." (PMID 31404102, 2019).
depression (3 papers, 2019 to 2023). "Based on previous studies, increased IGFBP5 expression in the prefrontal cortex of PD or depression has been suggested." (PMID 35513854, 2022). "Finally, we have found no study addressing peripheral IGFBP-4, IGFBP-5 and IGFBP-6 levels in the context of human depression." (PMID 37894932, 2023).
diabetic neuropathy (3 papers, 2015 to 2024). A chronic, pathological complication associated with diabetes mellitus, where nerve damages are incurred due to diabetic microvascular injury involving small blood vessels that supply these nerves, resulting in peripheral and/or autonomic nerve dysfunction. "Since sensory defects are a hallmark of diabetic neuropathy, we studied a sensory nerve (saphenous nerve) in IGFBP5-overexpressing mice in more detail and also tested behavioral parameters of sensory function." (PMID 26025657, 2015). "Overexpression of the IGFBP5 in mice has induced axonopathy and sensory deficits similar to those seen in diabetic neuropathy." (PMID 39844875, 2024). "IGFBP5 expression was also low in the 3 patients with non-diabetic neuropathy (P > 0.05, one-way ANOVA)." (PMID 26025657, 2015). "In diabetic neuropathy, 31 genes were studied in a single year, for example, HMGB1, IGFBP5 and SERPINF1 (PEDF)." (PMID 28761062, 2017).
heart failure (3 papers, 2014 to 2025). Inability of the heart to pump blood at an adequate rate to meet tissue metabolic requirements. "Previous studies have demonstrated that the expression of IGFBP5 is implicated in cardiovascular disease and even heart failure, which further suggests a novel role for IGFBP5 in the heart." (PMID 25230843, 2014). "In heart failure and myocardial infarction, IGFBP5 plays a dual role in fibrosis and repair, and also supports angiogenesis and cardiomyocyte survival under stress, highlighting its context-dependent roles." (PMID 40144669, 2025).
Impaired glucose tolerance (3 papers, 2015 to 2020). An abnormal resistance to glucose, i.e., a reduction in the ability to maintain glucose levels in the blood stream within normal limits following oral or intravenous administration of glucose. "Male IGFBP5-deficient mice are reported to have a greater body weight, impaired glucose tolerance at baseline and a larger increase in adipose tissue on a HFD compared to wild type." (PMID 33202914, 2020). "Besides important roles of IGFBP5 in cell survival and proliferation, it may also help regulate glucose homeostasis because Igfbp5-deficient mice exhibit impaired glucose tolerance." (PMID 31018536, 2019). "No changes in expression of IGFBP5 have been observed in SQ AT arrays from individuals with a BMI range of 16.7–50.2 kg/m2 and normal or impaired glucose tolerance (data set record GDS3961), supporting the notion that the induction seen in our study was due to pregnancy." (PMID 26067361, 2015).
keloid (3 papers, 2022 to 2025). An irregularly shaped, elevated mark on the skin caused by deposits of excessive amounts of collagen during wound healing. "HOXA11-AS and IGFBP5 expression was increased while miR-148b-3p expression was reduced in keloid and HKFs." (PMID 36046343, 2022).
oral cancer (3 papers, 2011 to 2022). "Antitumour effects of curcumin were found to be effective in another investigation in oral cancer cells, which triggered the promoter activity of insulin-like growth factor binding protein-5 (IGFBP-5) and CCAAT/enhancer-binding protein alpha (C/EBP-α)." (PMID 36247004, 2022). "In oral cancer, curcumin upregulates the expression of insulin-like growth factor binding protein-5 (IGFBP-5) by increasing the nuclear expression of CCAAT/enhancer-binding protein α (C/EBPα), which is a transcriptional regulator of IGFBP-5." (PMID 34867402, 2021). "In SAS oral cancer cells, curcumin induced the promoter activity of insulin-like growth factor binding protein-5 (IGFBP-5) and CCAAT/enhancer-binding protein alpha (C/EBPalpha), proteins involved in the suppression of head and neck cancers." (PMID 21299897, 2011).
osteoarthritis (3 papers, 2009 to 2024). A noninflammatory degenerative joint disease occurring chiefly in older persons, characterized by degeneration of the articular cartilage, hypertrophy of bone at the margins and changes in the synovial membrane. "MMP-13 and IGFBP-5 are important factors involved in osteoarthritis (OA)." (PMID 19948051, 2009). "A study conducted in dogs treated with protease inhibitors showed that increased levels of intact IGFBP5 result in an improvement in joint architecture during development of osteoarthritis, indicating a negative role of increased levels of PAPPA." (PMID 38479789, 2024).
sarcopenia (3 papers, 2022 to 2025). Progressive decline in muscle mass due to aging which results in decreased functional capacity of muscles. "By elucidating the broader role of IGFBP5 in fibrotic disorders, our study not only advances understanding of its mechanisms in sarcopenia but also highlights its relevance across multiple diseases." (PMID 40144669, 2025). "While our study focuses on the role of IGFBP5 in skeletal muscle fibrosis and sarcopenia, its involvement in fibrosis extends to multiple tissues and disease states, highlighting its potential as a therapeutic target." (PMID 40144669, 2025). "This study found that the IGFBP5 target may regulate the progression of fibrosis and sarcopenia in aging skeletal muscle through the IGF-1 pathway." (PMID 40144669, 2025). "However, the role of IGFBP5 in sarcopenia remains to be elucidated." (PMID 40144669, 2025). "Subsequently, we found that reducing the expression of IGFBP5 partially alleviated fibrosis in sarcopenic muscle by moderately potentiating the effects of IGF-1, providing clue to the development of novel anti-fibrosis therapies in sarcopenia." (PMID 40144669, 2025).
squamous cell carcinoma (3 papers, 2012 to 2022). A carcinoma arising from squamous epithelial cells. "IGFBP5 -1195T>C polymorphism is functional and could be a biomarker for susceptibility to late-stage squamous cell carcinoma of the head and neck." (PMID 36465383, 2022). "Increased IGFBP2 and IGFBP5 mRNA levels were correlated with increased overall survival in squamous cell carcinoma patients." (PMID 36465383, 2022). "Human squamous cell carcinoma NCI-H520 and murine lung adenoma LA-4 cell lines were transfected with vectors encoding murine Igfbp5 or Igfbp2 and, after selection with blasticidin, were scored for colony formation." (PMID 22973541, 2012).
Alzheimer disease (2 papers, 2022 to 2024). A progressive, neurodegenerative disease characterized by loss of function and death of nerve cells in several areas of the brain leading to loss of cognitive function such as memory and language. "Recently, Igfbp5 was found to be upregulated in the hippocampus and cortex of an Alzheimer's disease mouse model and in the cerebrospinal fluid of Alzheimer's disease cases, suggesting a pathogenic role of IGFBP5 in this disease." (PMID 35513854, 2022). "This could explain the high upregulation of IGFBP5 protein levels at early stages of Alzheimer Disease when synaptic plasticity still could occur." (PMID 35513854, 2022). "In the present work, we investigated the expression of IGFBP5 in the hippocampus of Alzheimer’s disease postmortem brain and tested in mice the effects of elevated Igfbp5 expression on hippocampal Bdnf protein levels and whether Igfbp5 might impair with the effects of exercise on cognition." (PMID 35513854, 2022). "However, this mTOR dependent IGF-1/IGFBP5 signaling pathway has not yet been studied in the hippocampus in the context of Alzheimer’s disease and needs further investigation." (PMID 35513854, 2022).
brain tumor (2 papers, 2023 to 2024). "To this end, we developed a CRISPR/Cas9-based nanocapsule that can be intravenously injected and actively target to the brain tumor for in vivo IGFBP5 gene editing, based on our previous report." (PMID 36949068, 2023). "Importantly, we found that IGFBP5 showed remarkable higher expression in brain tumor tissue than normal brain tissue, and our RNA-seq data revealed increased IGFBP5 expression in invasive GSCs compared with non-invasive GSCs, which suggests that the IGFBP5 signaling axis regulates GSC invasion." (PMID 36949068, 2023). "Using a GSC-derived brain tumor model, GSCs were characterized into invasive or non-invasive subtypes, and RNA sequencing analysis revealed that IGFBP5 was differentially expressed between these two subtypes." (PMID 36949068, 2023).
cardiomyopathies (2 papers, 2020 to 2022). "We further evaluated the protein expression of 5 miR-143 targets (HK2, ERK5, IGF1R, IGFBP5 and ORP8) that have been shown to be involved in cardiomyopathy or cardiac remodeling." (PMID 32855642, 2020). "In addition, ferroptosis-related genes could provide us with a novel direction of exploration in HCM and DCM, respectively, and 3 hub genes (POSTN, IGFBP5, and FMOD) could be potential biomarkers or therapeutic targets in cardiomyopathies." (PMID 35282347, 2022).
cervical intraepithelial neoplasia (2 papers, 2009 to 2022). "IGFBP5 expression is down-regulated in invasive cervical carcinoma and up-regulated in cervical intraepithelial neoplasia." (PMID 36465383, 2022).
coronary heart disease (2 papers, 2017 to 2021). "Young patients with coronary heart disease have significantly higher serum IGFBP5 than age- and BMI-matched controls." (PMID 28450971, 2017).
dyslipidemia (2 papers, 2014 to 2025). "Adam9 is an insulin-like growth factor binding protein-5 protease associated with adiponectin, which may modulate the development of the metabolic syndrome." (PMID 24675842, 2014).